RAB10 (RAB10, member RAS oncogene family)
Diseases named in the same sentence as RAB10 in open-access papers (continued):
Sharing a sentence is not in itself a finding about the gene and the disease.
infection (continued). "Prolonged retention of Rab10 on membranes suggests a defect in termination of the tubulation reaction, which could be targeted by CMV-encoded functions expressed in the E phase of infection." (PMID 39866842, 2024). "Indeed, as early as 10 min post-infection (p.i.), we could observe the complete disassembly of tubules in one region of the cell and recruitment of RAB10 to distal STm invasion sites." (PMID 38600106, 2024). "However, during infection by wildtype STm, SopD inhibits RAB10 through its GAP activity." (PMID 38600106, 2024). "Thus, it will be important to determine whether inhibition of Rab10 by SopD and/or SopD2 impacts the later stages of infection of host cells." (PMID 34349110, 2021). "To gain insight into how P. aeruginosa infection promotes RAB-10 activity, we sought to analyze the subcellular localization of DENN-4 and LET-413 following infection." (PMID 39087719, 2025). "Then, we identified UNC-16 as a RAB-10 effector situated on sorting endosomes, and the depletion of UNC-16 was accompanied by a decrease in DAGs and a weakened infection response." (PMID 39087719, 2025). "As Rab10 is one of the plausible substrates located on the LCV, we assessed its ubiquitination upon infection with the L. pneumophila strains for comparison between its GTP-bound active (QL) and GDP-bound inactive (TN) conformations." (PMID 38771316, 2024). "Upon infection of HEK293T-FcγRII cells transiently expressing FLAG-Rab10 and HA-Ub with a wild-type L. pneumophila strain (Lp01) for 1 hr, Rab10 was detected with a shifted band of higher molecular mass." (PMID 38771316, 2024). "During infection, SopB mobilizes membrane reservoirs and recruits EXOC2 from RAB10+ membrane reservoirs to invasion sites via its catalytic activity." (PMID 38600106, 2024). "Knockdown of either Rab10 effector (confirmed by qRT-PCR) reduced the number of infected cells with GFP-Rab10+ positive tubules during ΔsopD mutant infection." (PMID 34349110, 2021). "Our results revealed a considerable decrease in the survival rate of rab-10(ok1494) mutant animals when exposed to P. aeruginosa strain PA14, suggesting that the lack of RAB-10 increased susceptibility to infection." (PMID 39087719, 2025). "To investigate whether the biotin ligation response occurs at the sites of Rab10 accumulation, we exposed MCMV-infected cells to biotin for 18 h during the early phase of infection." (PMID 39866842, 2024). "The presence of IN1 from 4 h of infection neither prevented the Golgi compacting and displacement, nor the accumulation of Rab10 and Evectin-2 (data not shown)." (PMID 34440603, 2021). "Here, we show that RAB10+ membrane reservoirs contain some, but not all exocyst subunits prior to infection, and different exocyst subunits are trafficked from different cellular compartments to STm invasion sites separately, instead of as a pre-assembled complex." (PMID 38600106, 2024). "However, the level of Rab10 recruitment to the ΔsidCΔsdcA LCV recovered at 4 hr after infection, while that to the ΔsidCΔsdcAΔsdcB LCV did not recover even as late as 7 hr." (PMID 38771316, 2024). "It has been proposed that TBC-11/AS160/TBC1D4 acts as a GAP (GTPase activating protein) for RAB-10; however, the mRNA level of TBC-11 was not noticeably affected by infection." (PMID 39087719, 2025). "and infected cells immediately after infection with Δm138-MCMV (0 hpi), no cells positive for IE1 were detected, and Rab10 staining showed faint dispersed cytoplasmatic signal without juxtanuclear accumulation." (PMID 34440611, 2021). "Therefore, under normal infection conditions SopD-mediated inactivation of Rab10 may have the dual benefit of i) releasing Rab10-mediated stabilization of plasma membrane invaginations and ii) simultaneously promoting recruitment of Dynamin-2 via its ability to bind GDP-bound Rab10." (PMID 34349110, 2021).
infection (continued). "Despite the Golgi reorganization, which may be initiated by infection or by PYR-41 treatment, no expansion of Rab10-decorated membrane compartments was observed at 12 hpi, indicating that ubiquitination-dependent processes are required for the establishment of the inner pre-AC composition." (PMID 40868860, 2025).
cancer (15 papers, 2014 to 2025). A tumor composed of atypical neoplastic, often pleomorphic cells that invade other tissues. "Among these, Rab10 is a member of the small GTPase family, involved in intracellular membrane transport, and has been shown to play a crucial role in cancer progression, Alzheimer’s disease, and tuberculosis." (PMID 39996735, 2025). "The data stem from the Oncomine database indicated that the expression of RAB10 gene was more in HCC than in non-cancer tissues." (PMID 38364252, 2024). "In various types of human cancer cells, α3NaK is found to be aberrantly expressed in intracellular vesicles in which Rab10, a small GTPase, is localized." (PMID 38561668, 2024). "ACSL3, AIFM2, HSD17B7, LPCAT1, LSS, PLIN3 and RAB10 were up-regulated with the progression of cancer stage of HCC patients, while CIDEB, G0S2, HSD17B13, PLIN1 and PLIN2 were down-regulated." (PMID 37464334, 2023). "We conducted a pan-cancer analysis of RAB10 mRNA expression using the TNMplot database, which revealed its aberrant expression in a variety of tumors, including BC." (PMID 37709911, 2023). "The first eight of the nineteen targets, PIAS3, p27, RAB10, DBF4, DUSP14, RBPMS, PDPN and CLTC, were considered to be closely associated with cancer progression after a literature review." (PMID 28120918, 2017). "A future RAB10 inhibitors could correspond to a new therapeutic solution for patients with cancer with SMAD4 deletion." (PMID 37377893, 2023). "Four genes, RAB10, KLF5, TCF7L2, and CTNNB1 had gene essentiality strongly correlated with both SMAD4 mutation and SMAD4 CNA in various cancer cells (i.e., genes that are more essential when SMAD4 copy number is decreased or when SMAD4 is mutated, P values inferior to 1E-04)." (PMID 37377893, 2023). "Some Rabs, such as Rab1b, Rab4b, Rab10, Rab22a, Rab24, and Rab25, are dysregulated in many cancers." (PMID 24587032, 2014). "MicroRNA-378d (miR-378d) is involved in various biological processes and diseases, including the regulation of cell autophagy and apoptosis, as well as the inhibition of cancer cell growth and invasion, by regulating the expression of genes such as Gli3, SDAD1, and Rab10." (PMID 39996735, 2025). "Previous studies have shown that RAB10, RAB11A, RAB17, and RAB25 could promote cell proliferation in different cancers." (PMID 35154286, 2022).
neurodegenerative disease (2 papers, 2023 to 2024). A disorder of the central nervous system characterized by gradual and progressive loss of neural tissue and neurologic function. "Furthermore, we note that some studies have shown that Rab10 hyperphosphorylation may be associated with the development of neurodegenerative diseases in some cases." (PMID 39500355, 2024). "Therefore, maintaining the normal phosphorylation status of Rab10 may be of potential benefit in the prevention or treatment of neurodegenerative diseases associated with dysfunction of the Golgi-lysosome pathway." (PMID 39500355, 2024). "Despite diverse roles in neuronal function and involvement in neurodegenerative diseases, it is not known in detail where Rab10 and pRab10 are localized in the brain, likely because of its relatively low expression levels." (PMID 38110990, 2023).
bacterial infection (1 paper, 2020). "To further analyze the potential interplay between Lem27 and the SidC family E3 ligases during bacterial infection, we established a macrophage cell line that stably expresses mCherry-Rab10." (PMID 33136002, 2020).
movement disorder (1 paper, 2022). Neurological conditions resulting in abnormal voluntary or involuntary movement, which may impact the speed, fluency, quality and ease of movement. "Effect estimates adjusting for sex, age, disease duration, diagnosis, and baseline clinical scores identified increasing total Movement Disorder Society‐Sponsored Revision of the Unified (MDS‐UPDRS) scores (β = 0.77; CI, 0.52–1.01; P = 0.0001) with each fold increase of pT73‐Rab10 to total Rab10." (PMID 35521944, 2022).
RAB10 also shares sentences with these, for which no sentence is quoted: Parkinson's (7 papers); cervical cancer (3); lung adenocarcinoma (2); lung carcinoma (2); nervous system diseases (2); acute kidney injury (1); bladder cancer (1); Bradykinesia (1); brain injury (1); cardiovascular disease (1); cognitive decline (1); depression (1); diabetic (1); endometrial cancer (1); essential hypertension (1); Genetic disorders (1); glioblastoma (1); Huntington disease (1); Hyperglycemia (1); Insulin resistance (1); invasive breast carcinoma (1); Jaundice (1); kidney disease (1); leukemia (1); liver diseases (1); ovarian carcinoma (1); pterygium (1); stomach cancer (1); systemic lupus erythematosus (1); thyroid cancer (1).
A further 1 disease shares a sentence with RAB10 in 1 paper.